IFNG (interferon gamma)
Diseases named in the same sentence as IFNG in open-access papers (continued):
Sharing a sentence is not in itself a finding about the gene and the disease.
cancer (continued). "Furthermore, single-cell sequencing datasets allowed for the separation of cancer cells and healthy cells from the same tissue biopsy and the characterization of a microenvironment containing interferon gamma excreted by EBV-stimulated T-lymphocytes." (PMID 38352479, 2024). "Then Th1 cells released TNF-α and Interferon gamma (IFNγ) which act as cancer suppressors." (PMID 39252305, 2024). "However, it is widely accepted that this binary classification of macrophages on anti-cancer M1 and pro-cancer M2 is oversimplified and can be seen only in vitro as a result of stimulation of activated monocytes with bacterial LPS/IFNγ or IL-4." (PMID 38794298, 2024). "Importantly, at least one cancer immunotherapy by activating (IFNγ)(pSTAT1) and inhibiting (TGFβ)(pSTAT3) is currently in preclinical and clinical studies (NCT02786589, NCT03474822, NCT03375983, and NCT05924776)." (PMID 38807760, 2024). "Collectively, these findings demonstrate the profound impact of IFNγ on tissue-specific trained immunity, which could have direct implication in mucosal cancer therapies." (PMID 39081326, 2024). "Interferon-gamma (IFN-γ), one of the cytokines produced, directly inhibits cancer growth, enhances the visibility of cancer cells to the immune system by upregulating MHC molecule expression, and activates other immune cells like macrophages and NK cells to join the fight against the cancer." (PMID 39155358, 2024). "Similarly, cocultures using CD8 + T cells from mice that received VSV-FAST viruses alone or in combination with immunotherapy exhibited increases in the release of the proinflammatory anti-cancer cytokines IFNγ and TNF into the culture supernatant." (PMID 38750591, 2024). "CD8+ cells have a tumoricidal effect on cancer cells via an interferon-gamma-mediated mechanism." (PMID 38779258, 2024). "IFNγ also upregulates pro‐apoptotic factors in cancer cells." (PMID 39324702, 2024). "Given that increased CD8+ T cell infiltration has been associated with an improved response to anti-PD-1 immunotherapy agents in other forms of cancer, gene expression profiling and the interferon gamma gene expression signature assay have been developed to measure the degree of T cell activation." (PMID 38398094, 2024). "Furthermore, PD-L1 expression on the cancer cell membrane can be induced through the IFNγ and pro-inflammatory immune response." (PMID 39199657, 2024). "In addition, immunotherapy-activated CD8 T cells induce ferroptosis in cancer cells via interferon gamma (IFNγ) and IFNγ receptor I axis." (PMID 38429255, 2024). "IFNγ functions as a key regulator of PD-L1 in both immune as well as cancer cells." (PMID 39099201, 2024). "In addition to OC cells, IFNγ likely regulates other cells in the TME, including TILs, TAMs, dendritic cells (DCs), myeloid-derived suppressor cells (MDSCs), as well as cancer-associated fibroblasts (CAFs), thus having a central regulatory function in the TME." (PMID 39123403, 2024). "Over-expression of TP63 may serve as a biomarker predicting the outcome of SCC patients treated with ICB therapy, and targeting TP63/STAT/IFNγ axis may enhance the efficacy of ICB therapy for this deadly cancer." (PMID 38509096, 2024). "To investigate the effector function of our TCR-Ts against EC, we set up in vitro cytotoxicity and IFNγ release assays where we co-cultured our TCR-Ts with varying cancer cell lines or TCR-Ts with T2 cells pulsed with various antigenic peptides at E:T ratios 1:1 or 2:1." (PMID 38336680, 2024). "However, oxaliplatin seems to induce immunogenic signals on the surface of cancer cells before apoptosis, triggering interferon-gamma production and interaction with toll-like receptor 4 on dendritic cells, resulting in the immunogenic death of cancer cells." (PMID 38177168, 2024).
cancer (continued). "Natural killer (NK) cells are cytotoxic innate lymphocytes with an increasingly recognised role in the control of cancer via direct lysis of target cells and promotion of the anti-cancer immune response through release of proinflammatory cytokines such as IFNγ." (PMID 39286025, 2024). "However, IFNγ secretion, which was reduced in cocultures of PBMCs and cancer cells, was completely restored by TU2218 treatment and improved in a TU2218 concentration-dependent manner." (PMID 39105882, 2024). "In addition, IFNγ expression is induced in response to immune checkpoint blockade (ICB) or radiation therapy used in cancer treatment." (PMID 39123403, 2024). "Cancer cells in state 3, which positively responded to NAT, exhibited significantly elevated expression levels of immune-related genes, including those implicated in neutrophil activation, antigen processing and presentation, and response to IFNγ." (PMID 38566201, 2024). "In addition, IL-12 induces the release of IFNγ and has exhibited notable antitumor efficacy in numerous pre-clinical cancer models." (PMID 39204319, 2024). "Gene ontology (GO) term analysis highlighted the enrichment of signaling pathways related to the early and late responses to OVs in cancer cells including interferon gamma and alpha response, TNF signaling via NF-κB and apoptosis that were all being affected by the 4-OI treatment." (PMID 38750019, 2024). "In addition, PD-L1 expression in cancer cells can be induced by IFNγ produced in response to chemotherapy, radiation or immune checkpoint blockade used in cancer treatment." (PMID 39123403, 2024). "Moreover, a decrease in IFNγ expression levels is observed in T cells in cocultures of human PBMCs and cancer cells." (PMID 39105882, 2024). "Apart from the surface markers, blocking O-GlcNAcylation also decreased the cytokines tumor necrosis factor and interferon gamma (IFNG) and the death mediators, FasL, perforin, granzymes, and granulysin and compromised the cancer cell killing potential of both primary NK cells and NK-92 cells." (PMID 38718861, 2024). "In GSEA, TPST2 knock-down resulted in the depletion of cell cycle-related genes, such as ‘E2F_TARGETS’, ‘G2M_CHECKPOINT’, ‘MYC_TARGETS’, and ‘MITOTIC_SPINDLE’, which is suggestive of enhanced IFNγ signaling, because IFNγ signaling is involved in the anti-proliferative effect on the cancer cells." (PMID 39095793, 2024). "A recent study demonstrated that IFNγ promotes stemness in cancer cells, supporting the idea that the IFNγ pathway might also be important for cellular dedifferentiation in other contexts, highlighting the broader relevance of our findings." (PMID 39110794, 2024). "IFNγ has been shown to have direct antiproliferative effects in human cancer cell lines." (PMID 38635884, 2024). "Moreover, IFNγ expression can diminish NKG2D ligands on cancer cells to avoid NK cell-based killing." (PMID 38216787, 2024). "From this narrative review of the actual scientific landscape, Interferon-gamma (IFN-γ) emerges as a central player, demonstrating a dual role in both promoting and inhibiting cancer immunity, but the work navigates through all the major interleukins known in inflammatory environments." (PMID 38607023, 2024). "Alternatively, DCPs may orchestrate an IFNγ-dependent, endogenous immune response that eliminates cancer cells escaping recognition and killing by CAR-T cells." (PMID 37996514, 2024). "In addition, the genes in the hallmarks gene set ‘Apoptosis’ were enriched in TPST2 knock-down cells, which is suggestive of enhanced IFNγ signaling, because IFNγ signaling is known to exert pro-apoptotic effects on cancer cells." (PMID 39095793, 2024). "IFNγ is a pleiotropic cytokine that plays a major role in the immune response and cancer immunity." (PMID 39123403, 2024).
cancer (continued). "However, this phenomenon is not uncommon as it is also known that the expression of PD-L1, the immune-suppressive ligand for PD-1, is also upregulated by IFNγ, an essential cytokine for T cell function in host cancer immune surveillance." (PMID 38995014, 2024). "Because of these antitumor properties, IFNγ has been used in cancer treatment." (PMID 39123403, 2024). "Previous studies have demonstrated that CD8 + T cells could be build ferroptosis sensitization in cancer cells by secretion of IFNγ." (PMID 37369808, 2023). "However, IFNγ modulation for cancer therapy is still unsuccessful due to its complex effects on various host cells." (PMID 37056922, 2023). "It was concluded that the cancer cell spheroid secretome is affected by IFNγ/Pam3SCK4 and IL-4." (PMID 37445941, 2023). "IFNγ, for example, is known to be secreted by TH cells, cytotoxic T lymphocytes, and natural killer cells and has both a pro- and antitumor immune response in cancers." (PMID 36675138, 2023). "Finally, few IFNG+CD8+ T cells were predicted to possess shared-cancer antigen or self-antigen specific TCRs, showing a higher expansion in MSS CRC or MSI CRC respectively, albeit non-significant." (PMID 37968259, 2023). "In fact, IFNγ pathway could be one of feasible pathways, which causes the PDL1 upregulation in cancers." (PMID 39282109, 2023). "Therefore, the challenge for IL12 and IFNγ immunotherapies for the treatment of cancer is to be able to trigger a strong recruitment and activation of anti-cancer adaptive immunity within the TME while minimizing the toxicity." (PMID 36854896, 2023). "Analysis using the ‘Cancer Hallmark’ gene set indicated that the top pathways suppressed by JGT in SI rats were IFNα and IFNγ, and inflammatory responses and IL6/JAK/STAT3 signaling, that is, the same pathways that were activated in SI rats compared with GH rats." (PMID 36980301, 2023). "Effector CD4+ accumulating in the TME also support cancer immunity through the secretion of inflammatory cytokines (i.e., IFNγ and tumor necrosis factor alpha), production of IL-2 necessary for CD8+ T cell maintenance, and by providing help to B cells through CD40L co-stimulation." (PMID 37081897, 2023). "In addition, IFNγ also induces programmed cell death ligand 1 (PD-L1) expression on cancer cells, which promotes immunosurveillance and is associated with the poor prognosis of HPV-negative HNSCC patients." (PMID 37685940, 2023). "IFNγ was able to target cancer cells by suppressing system Xc- and lead to ferroptosis as a result." (PMID 37182170, 2023). "Because of its anticancer properties, IFNγ has been used in cancer treatment." (PMID 37151134, 2023). "Growth arrest of cancer cells can be achieved by inducing senescence through cytokines like IFNg." (PMID 36776340, 2023). "The occurrence of cancer-related muscle loss is profoundly influenced by cytokine-mediated inflammation, specifically involving TNF-α, interleukin-1 (IL-1), IL-6, and interferon-gamma (IFNγ)." (PMID 37959329, 2023). "Furthermore, IFNγ has also been shown to directly enhance NK cell-mediated induction of cancer cell death by apoptosis and cytolysis." (PMID 37370779, 2023). "Extrinsic IFNγ can upregulate PD-L1 expression in various cancer cells, including CC cells." (PMID 37316937, 2023). "The impact of IFNγ on CysLT receptors, specifically CysLT1R, has been shown by various researchers, including us, in immune cells, bronchial smooth muscle cells, and cancer models." (PMID 37316937, 2023). "Moreover, our group has previously documented a significant shorter PFS in cancer patients with decreasing plasma levels of IFNγ within the first two months of treatment." (PMID 37816781, 2023). "Moreover, many cancer types shared immune-related functions, like activation of innate immune response, interferon gamma response and NOD-like receptor signalling pathway." (PMID 36945884, 2023).
cancer (continued). "Animal models of neuroinflammation in the context of cancer and treatment with radiation therapy and immunotherapy indicate changes also may occur in interferon gamma (IFNγ) and fibroblast growth factor-basic (bFGF) levels." (PMID 36900405, 2023). "Because resistance to ICI therapy is observed in many solid tumors, we determined whether Ptpn2 inhibition sensitizes other cancers to IFNγ treatment." (PMID 36968224, 2023). "Because of its antitumor potential, IFNγ has been used in cancer treatment." (PMID 37151134, 2023). "It is theoretically possible that a leaky amount of activation factors (IL4, or IFNγ/Pam3SCK4) are present in the (w/o) macrophage environment and may interact with the cancer cell spheroid." (PMID 37445941, 2023). "In addition, we also noted that SRSFs expression was correlated with the activation or inhibition of multiple immune-related pathways in different cancer types, such as interferon alpha response, interferon gamma response, Il-6/JAK/STST3 signaling and so on." (PMID 38015716, 2023). "Moreover, several recent studies have shown that defective IFNγ signaling in cancer cells leads to resistance to immunotherapy with checkpoint inhibitors." (PMID 37991387, 2023). "In addition, IFNγ expression can be induced in response to radiation therapy or immune checkpoint blockade (ICB) used in cancer treatment." (PMID 37151134, 2023). "In cancer patients vaccinated against SARS-CoV-2, the cell-mediated immune response has been assessed through enzyme-linked immunosorbent spot (ELISpot) tests to identify IFNγ-producing specific T cells." (PMID 37509286, 2023). "Unfortunately, and given that we used a large collection of drugs covering most biological pathways, our results suggest that the chemical-induction of HLA-I expression in cancer cells harboring mutations that disable IFNγ signaling is unlikely to succeed." (PMID 36743451, 2023). "In addition to its upregulation of antigen processing and presentation, JQ1 also promoted Interleukin‐2 (IL2) family signaling, interferon‐γ (IFNG) signaling, and cytokine signaling in cancer cells." (PMID 37271874, 2023). "IL4I1 is expressed by cancer cells in response to IFNγ and TNF-α." (PMID 36834576, 2023). "Importantly, upon integration they appeared to be functional as they did blunt the anti-proliferative effect of trastuzumab on BT-474 cancer cells and responded to IFNγ treatment with differentiation toward M1-like phenotype." (PMID 37346794, 2023). "T-cell-derived IFNγ in the co-culture medium contributes to cancer cell autosis." (PMID 37091978, 2023). "IFNγ-mediated PD-L1 activation in various cancers occurs via STAT1 phosphorylation." (PMID 37316937, 2023). "Importantly, CD19+CD24hiIgDlo/−CD38lo and CD19+CD24hiIgDlo/−CD38hi Bregs from cancer patients showed a significantly stronger ability to inhibit T cell activation (as measured by IFNγ production) than those from healthy subjects (left)." (PMID 37291146, 2023). "Next, we determined if NAMPT was induced in other cancer types in response to IFNγ." (PMID 36900204, 2023). "The role of type I NKT cells in protection against cancer has been found to be largely dependent on production of Th1 cytokines, especially IFNγ, even though NKT cells have lytic activity and could potentially directly lyse tumors expressing CD1d." (PMID 37529610, 2023). "Since the levels of PD‐L1 and IL‐8 correlate in cancer patients, we hypothesized that the IFNγ‐induced IL‐8 expression in OC cells might be also mediated by Bcl3." (PMID 37151134, 2023). "Recently, other cytokines have been described as being involved in the pathophysiological mechanism of cancer cachexia: TNF receptor (TNFR)-associated factor 6 (TRAF6), TNF-like inducer of apoptosis (TWEAK), leukemia inhibitory factor (LIF), and interferon-gamma (IFN-γ)." (PMID 38067294, 2023).
cancer (continued). "Recombinant IFNγ (ACTIMMUNETM) is approved for the treatment of infections associated with chronic granulomatous disease, but has also extensively been studied in cancer patients [NCT00004032, NCT00004016, NCT02614456]." (PMID 36839699, 2023). "Interferon-gamma (IFNγ) exerts potent growth inhibitory effects on a wide range of cancer cells through unknown signaling pathways." (PMID 37803324, 2023). "Thus, our data suggest that AC484 increases the sensitivity of nearly all human cancer cell lines to IFNγ and inhibits the growth of cancers that exhibit features of intrinsic inflammation." (PMID 37794185, 2023). "Understanding the multiple factors that influence the abundance of peptides presented on HLA-I in the absence or presence of IFNγ is important to identify the best targets for antigen-specific cancer immunotherapies such as vaccines or T-cell receptor engineered therapeutics." (PMID 37991387, 2023). "A deeper understanding of IFNγ biology may be beneficial to generate novel engineered prototypes with improved curative anti-cancer potential." (PMID 36839699, 2023). "Indeed, IFNG signaling antagonizes both adaptive and innate immune responses through an inhibitory feedback circuit orchestrated by cancer cells." (PMID 36845750, 2023). "The insights from this study should ultimately lead to more accurate predictions of the immunopeptidome in cells exposed to IFNγ, information which could be valuable for cancer vaccine or TCR therapy designs." (PMID 37991387, 2023). "IFNG, a cytokine interferon-gamma, is known to mediate cancer immunoevasion." (PMID 37547766, 2023). "Overall, exogenous administration of type 1 immune cytokines for cancer treatments, particularly IFNγ and IL-12, are promising but may be limited by toxicities." (PMID 37455828, 2023). "This suggests that although MHC-II expression is usually restricted to APCs, it could also be expressed intrinsically in a subset of cancer cells or induced by IFNγ." (PMID 36869384, 2023). "Because TGFβ accumulation may occur at the invasive front in carcinomas, we simulated tumors with either a homogeneous TGFβ field or a TGFβ gradient, in the absence or presence of IFNγ inhibition (either by PD-L1 or by TGFβ)." (PMID 37638024, 2023). "Through in-depth analyses, we observed that the TRP score was positively associated with many malignant pathways in pan-cancer, such as IL6–JAK–STAT3 signalling, interferon-gamma response, and inflammatory response—all of which were closely associated with TIME." (PMID 35493463, 2022). "Tyk2 blocks induction of the IFNγ-regulated immune checkpoint Ido1 in Paneth-like cancer cells by an unknown mechanism." (PMID 36185806, 2022). "Thus, ISGs expressed by cancer and immune cells oppose each other, and IFNG.GS (immune cell)/ISG.RS (cancer cell) ratio correlates with the response of ICIs." (PMID 35432377, 2022). "On the other hand, CDKN2B-AS1 may be involved in the activation or shutdown of many cancer classic pathways, such as epithelial mesenchymal transition, allograft rejection, interferon gamma response, and inflammatory response." (PMID 35432631, 2022). "FBXO44 inhibition reactivates REs, leading to IFNγ signaling activation in cancer cells, as shown by the increased expression of IFNGR1, IFNGR2, and other ISGs and the decreased expression of protein tyrosine phosphatase nonreceptor type 2 (PTPN2), an IFNγ signaling inhibitor." (PMID 34385592, 2022). "The CAFDL signature was significantly positively associated with TGFB1, CD276, CD40, VEGFA, VEGFB, etc., but showed significantly negative correlation with immune checkpoints (such as CD274, PDCD1, CTLA4, TIGHT, and HAVCR2) and anti-cancer immune regulators (IFNG, IDO1, and GZMA)." (PMID 35967425, 2022).